CCR8 (C-C motif chemokine receptor 8)
Diseases named in the same sentence as CCR8 in open-access papers (continued):
Sharing a sentence is not in itself a finding about the gene and the disease.
tumor (continued). "Indeed, CCR8 has been shown to play a pivotal role in tumor progression by regulating the localization and function of Treg cells in murine cancer models." (PMID 34885241, 2021). "This analysis revealed that loss of CCR8 function does not affect the frequency or total number of Treg cells within tumours and spleens." (PMID 33838058, 2021). "To provide insight into these matters, we employed single-cell RNA-sequencing on the tumor T-cell infiltrate and identified two main ti-Treg subsets, one of which showing enhanced expression of CCR8 and various activation markers and displaying increased T-cell suppressive acitivity." (PMID 33589525, 2021). "Additionally, we discuss the possibility of targeting or deleting a key subset of Tregs that are CCR8+ Tregs and are highly dominant at the tumor site of several cold tumors." (PMID 34944943, 2021). "The recent identification of molecules, such as CCR8, that are specifically upregulated on these cells within tumors may provide novel therapeutic anchor points in multiple tumor types." (PMID 32014107, 2020). "Notably, the characteristic genes of Treg cells are highly expressed in whole tumor samples, for example, LAYN, MAGEH1 and CCR8 are associated with poor prognosis." (PMID 33614479, 2020). "Furthermore, administration of anti-CCR8 antibody in mice with transplanted colorectal tumors significantly inhibited tumor growth." (PMID 31811337, 2020). "It is involved in the recruitment of CCR8-CD11b+ myeloid cells and Treg to a tumor niche." (PMID 33076281, 2020). "In addition to PITPNM3, other receptors are also responsible for the CCL18-dependent migration and EMT of tumor cells, for instance CCR8 in bladder cancer cells." (PMID 33114763, 2020). "Some Tregs in draining LNs also expressed high CCR8 which might be ones earmarked for tumor infiltration or Tregs in micrometastases inside LNs." (PMID 29887862, 2018). "In multivariate analyses, CCR8 expression was identified as an independent prognostic factor (P = 0.008) and entered into a newly-built nomogram together with T stage, Fuhrman grade, tumor size, necrosis and lymphovascular invasion." (PMID 26716905, 2016). "Finally, linear regression modeling identifies major determinants of tumor immunogenicity, which include well-characterized modulators as well as a novel candidate, CCR8, which is then tested in an orthologous immunodeficient mouse model." (PMID 25853550, 2015). "In addition to classical immune checkpoints such as CTLA‐4 and PD‐1, as well as metabolism‐related molecules such as CD39/CD73, the chemokine receptor CCR8 has emerged as a highly promising therapeutic target because of its specific expression in tumor‐infiltrating Tregs (TI‐Tregs)." (PMID 41201063, 2025). "Moreover, when CT26 and MC38 tumor-bearing mice were treated with 225Ac-labeled anti-CCR8 antibody followed by anti-CTLA4 immune-checkpoint-inhibiting immunotherapy, the synergistic slowing down of tumor progression and increase in animal survival were observed." (PMID 41302499, 2025). "We speculated that highly activated Treg cells pre treatment represented an immune phenotype with more favorable tumor antigen recognition along with high Tex cells, while high CCR8+ Treg cells after immunotherapy represented an irreversible suppressive phenotype." (PMID 38897205, 2024). "Notably, CCR8 emerged as a key player in Treg migration within the tumor microenvironment." (PMID 39273290, 2024). "Furthermore, CCR8 recruits TAMs and Tregs, and promotes tumor angiogenesis." (PMID 36952458, 2023). "For example, CCR8 is a marker of multiclonal Tregs in tumors, which may play an immunosuppressive role, and the targeted depletion of CCR8-expressing cells may have potent anti-tumor effects." (PMID 36768342, 2023).
tumor (continued). "Following the lead of mogamulizumab, ADCC-active antibodies to CCR8 could bind to and eliminate tumor-associated Treg cells, notably the most activated and suppressive fraction of Treg cells that selectively express this chemokine receptor." (PMID 35158783, 2022). "Therefore, we investigated whether targeting CCR8 with CAR T cells significantly suppresses tumor progression in ATLL models." (PMID 35693763, 2022). "In naive and tumor-bearing mice, CCR8 expression could be detected on a fraction of thymic Tregs." (PMID 33589525, 2021). "Moreover, their selective accumulation within the tumor site may suggest that selective depletion of CCR4+ or CCR8+ Tregs may enhance anti-cancer immunity while having a very limited effect on Tregs in the periphery." (PMID 34944943, 2021). "Therefore, CCR8 may become a reasonable target for cancer immunotherapy, which is used to regulate tumor-resident Treg, enhance the anti-tumor immune response and prolong the survival of patients." (PMID 34884642, 2021). "Our findings therefore do not lessen the importance of CCR8 as a potential target in therapies aimed at selectively targeting tumour‐associated Treg cells, but suggest that therapeutic depletion of CCR8+ Treg cells rather than blockade of CCR8 function is likely to be more efficacious." (PMID 33838058, 2021). "To verify whether antigen recognition also results in CCR8 upregulation in vivo, we adoptively transferred CellTrace-labeled OT-II splenic Tregs into the tumor of LLC-OVA-bearing mice, resulting in the upregulation of CCR8 expression on a fraction of these cells." (PMID 33589525, 2021). "Interestingly, the expression of DCK was associated with the gene markers like CCR8, STAT5b, and TGFB1 of Tregs, and PD–1, CTLA–4, LAG3, TIM–3, and GZMB of exhausted T cells after adjusting tumor purity, revealing that increased expression of DCK was associated with immunosuppression in HCC." (PMID 32690026, 2020). "However, to what extent the tumor-infiltrating Treg signature and CCR8+ Treg are present within glioblastoma tumors is currently unknown." (PMID 32014107, 2020). "However, the expression of CCR8 in RCC remained unclear, despite a recent work showed that up-regulated expression of CCR8 is detected within RCC tissues and primarily limited to CD11b+ tumor associated macrophages, while their work enrolled limited 22 RCC patients." (PMID 26716905, 2016). "Novel approaches—such as bispecific antibodies designed to simultaneously target CTLA-4 and PD-1, as well as therapies directed against CCR8, GITR, and TIGIT—seek to selectively deplete or reprogram tumor-infiltrating Tregs." (PMID 40297580, 2025). "225Ac-anti-CCR8 RIT-treated tumors were analyzed immunohistochemically for FoxP3 and CCR8 expression while mechanistic studies of tumor-infiltrating lymphocytes were done by flow cytometry." (PMID 41035646, 2025). "The humanized monoclonal antibody S-531011, specific for CCR8, has been evaluated in murine colorectal carcinoma (CT26.WT) and breast carcinoma (EMT6) models, reinforcing tumor immunity through selective intratumoral Treg depletion." (PMID 41394821, 2025). "In glioma, elevated lactate levels induce the lactylation modification of CD73 in tumor cells, CD39 and chemokine receptor CCR8 in Tregs, CD39 in macrophage, and CD73 in T cells, reshaping the pro-tumor immune phenotype." (PMID 40589733, 2025). "The IHC results further demonstrated the more the CCR8+ cell infiltration, the less the presence of CD45+ immune cells, CD4+ cells, CD8+ cells, as well as CD56+ cells in the tumor tissues." (PMID 40186298, 2025). "Flow cytometry analysis further confirmed that CCR8+ Tregs highly express FOXP3 and CD25, along with immunosuppressive molecules such as CTLA4 and CD39, supporting their role as strongly suppressive tumor-localized Tregs." (PMID 41323783, 2025). "First, we used the WTA protocol to evaluate the infiltration of Tregs, CCR8+ Tregs, CD8+ T cells, and GzmB+ CD8+ T cells to the whole tumor area." (PMID 41323783, 2025).
tumor (continued). "CCR8 is a cell surface receptor belonging to class A of the G protein-coupled receptor (GPCR) family and is considered one of the best tumor Treg targets." (PMID 39329710, 2024). "CCR8 is the sole receptor for CCL1, and the CCL1‐CCR8 axis promotes tumour activity in various malignancies." (PMID 38506205, 2024). "CCR8 is the only receptor of CCL1, so CCL1 activation of the CCR8 receptor on tumor cells promotes their proliferation and metastasis." (PMID 39136031, 2024). "Using human tumour samples and murine subcutaneous tumour models, we demonstrated that TNF-α-induced TNFR2+CCR8+ Tregs were more immunosuppressive and able to dampen antitumour T cell responses, thus promoting tumour growth." (PMID 37935468, 2024). "To investigate the function of TNFR2+CCR8+ Tregs in the TME, we analysed the phenotypes and functions of tumour-infiltrating Tregs by FACS." (PMID 37935468, 2024). "Tumour-specific immune cells (CD8+ T cells, CD8+ T cells plus TNFR2+CCR8+ Tregs, or CD8+ T cells plus TNFR2−CCR8− Tregs) or the phosphate-buffered saline (PBS) control was injected into the CDX model five days after tumour inoculation." (PMID 37935468, 2024). "CCR8-DNR-CAR-T cells have a long survival and good proliferation ability at the tumor site, and the therapeutic effect on the tumor has also been significantly improved." (PMID 39136031, 2024). "This study focused on the interactions between CCR8+ Tregs and CD8+ T cells in the LSCC TME, evaluating the impact of their spatial distribution on anti-tumor immunity by histological analysis." (PMID 38783281, 2024). "In vivo, anti-mouse CCR8 antibodies effectively depleted Tregs within the TME primarily via ADCP, leading to increased CD8+ T cell infiltration and subsequent tumor growth inhibition across various cancer models." (PMID 38856863, 2024). "Here, we reported that in both MC38 cell-based and CT26 cell-based tumour models, anti-PD1 treatment induced CCR8+ Treg infiltration, thus promoting immune escape." (PMID 37935468, 2024). "Treg cells highly express certain chemokine receptors (CCR4, CCR5, CCR8, CCR10), which facilitates their preferential migration to the tumor microenvironment." (PMID 38500876, 2024). "Immunofluorescence staining of tumour tissue showed that TNFR2 and CCR8 were coexpressed in FOXP3+ Tregs." (PMID 37935468, 2024). "CCR8 is highly expressed on NLT-resident Tregs, including those in tumors, and is considered a suitable target for tumor-infiltrating Treg depletion." (PMID 38341270, 2024). "This contradicts a study revealing a decrease in TITR number at tumor sites by IPG7236, a selective CCR8 antagonist." (PMID 38231448, 2024). "Our research further found that histone lactylation upregulated CD39, CD73 and CCR8 expressions, which clarified a mechanism of immunosuppressive TME formation induced by the high concentration of lactate produced by tumor metabolism." (PMID 37770937, 2023). "Similar to our observations in mouse, CCR8+ FOXP3− Tconv cells expressed high levels of CD25 and were significantly enriched in tumor tissue compared to healthy adjacent tissue and blood from the same patients." (PMID 38100544, 2023). "The ligand of CCR8, CCL1, enhances tumor immunosuppressive microenvironment via the recruitment of CCR8+ Treg cells." (PMID 37072770, 2023). "Studies have shown that Tregs express a variety of chemokine receptors, such as CCR4, CCR5, CCR8 and CCR10, which can respond to a variety of chemokines released during tumor growth, and then participate in the migration of Tregs to tumor tissues." (PMID 37950246, 2023). "Consistent with previous reports, CCR8 is hyperexpressed on Tregs, and its ligand, CCL4, secreted by M2 macrophages, has been demonstrated to recruit Tregs to the tumor niche in other cancers." (PMID 35562760, 2022).
tumor (continued). "CCR4, CCR8, CCR10, and CXCR3 induce Treg cell migration to the tumor microenvironment in response to CC and CXC chemokines: CCR4 is bound by CCL17 and CCL22, CCR8 is bound by CCL1, CCR10 is bound by CCL28,and CXCR3 is activated by CXCL9/10/11." (PMID 36012113, 2022). "However, chemokine receptor CCR8 was highly expressed by Treg cells in later-stage GC patients in comparison to that in earlier-stage GC patients, indicating a strong chemotaxis of tumor cells or microenvironment components on Tregs in GC patients with advanced stage." (PMID 35874784, 2022). "Equally important, the fraction of peripheral blood CCR8+ Treg cells (approx. 40% of all FoxP3+ Treg cells) are phenotypically similar to tumor CCR8+ Treg cells and share many TCR clonotypes with tumor CCR8+ Treg cells." (PMID 35158783, 2022). "SPI1 expression was positively and strongly associated with T cell exhaustion markers (LAG3 and PDCD1,), and Treg cell markers (FOXP3 and CCR8), suggesting that high SPI1 expression level inhibits anti-tumor immunity." (PMID 36477668, 2022). "The introduction of CCR8 and DNR into CAR T cells provides more effective solid anti-tumor activity." (PMID 35326556, 2022). "We measured the expression of CCL18, CCR8 and PITPNM3 in the GMB tumor from patients (16 men and 12 women) using quantitative real-time polymerase chain reaction." (PMID 35955670, 2022). "To formally test the function of CCR8 in Treg cell accumulation within tumours, we examined the frequency and number of Foxp3+ Treg cells within MC38 tumours implanted in WT and Ccr8−/− animals." (PMID 33838058, 2021). "Both CCR8 and P2RY14 gene expression was significantly correlated with pathological tumor stage, T-stage, and gender (P<0.05)." (PMID 33692955, 2021). "Therefore, the function of CCR8 in tumour immunity remains unclear." (PMID 33838058, 2021). "Among them, there were significant differences in the expression of CCR8 and P2RY14 in tumor tissues and normal tissues." (PMID 33692955, 2021). "CCR8 is uniquely upregulated on intratumoral Tregs and, thus, forced expression of CCR8 enhanced CAR T cell trafficking to tumor while the DNR prevented suppression by TGF-β." (PMID 34868044, 2021). "Together, these results demonstrate that CCR8 upregulation on ti-Tregs is induced in an NF-κB dependent manner and initiated by TCR stimulation through tumor antigen recognition." (PMID 33589525, 2021). "CCR8 and P2RY14 were differentially expressed in tumor tissues than normal tissues, and the results were validated at the protein level by immunohistochemistry experiments." (PMID 33692955, 2021). "However, CCR8 was found to be only highly enriched in tumor Treg cells and were much less abundant in Tconv cells, suggesting that Treg and Tconv cells may embrace both distinct and shared pathways to maintain their chemotaxis to the breast tumor microenvironment." (PMID 34868991, 2021). "The production of inflammatory cytokines such as PDGF, TNFa, CCR8, and CCR2 within the solid organ tumor microenvironment, has been shown to enhance homing of MSCs to the tumor location." (PMID 34713241, 2020). "To test if CTLA-4 levels in tumor-infiltrating cells are higher among activated Treg, we analyzed CTLA-4+ cells for their cell surface CCR8." (PMID 31991588, 2020). "Studies regarding Treg chemotaxis through chemokine ligand 1 (CCL1)‐chemokine receptor 8 (CCR8) and CCL22‐CCR4 into the tumor microenvironment (TME) have been performed." (PMID 33519807, 2020). "The authors further focused on CCR8, and showed that its surface expression was restricted to Treg cells and to a subset of natural killer T cells among CD45+ and non‐CD45 cells within tumours." (PMID 31032905, 2019). "Lastly, in order to make the newly obtained knowledge easily accessible to experimental immunologists, we showed the expression of NFAT5, IL2RA, CCR8, BCL6, and KCNK5 in the tumor-infiltrating T cells in a flow cytometric format." (PMID 30061879, 2018).
tumor (continued). "CCR8 expression was exclusively enriched on TI-Tregs, whereas CCR2, CCR4, and CCR5 expressions were found on other tumor-infiltrating and/or peripheral blood Tconv cells as well." (PMID 29887862, 2018). "The danger signals thereby induce the production of inflammatory cytokines such as PDGF, TNFα, CCR8, and CCR2 within the tumor microenvironment, and consequently enhance MSCs swarming into the tumor location(s)." (PMID 29326689, 2017). "Since, induced FoxP3 are downregulated for CCR7 and CD62L as well as upregulated for memory or effector-type trafficking receptors such as CCR4, CCR5, CCR8, CCR10, and/or CXCR4, they can migrate into the tumor via the tumor-draining lymph nodes." (PMID 29450136, 2017). "Other chemokine receptors implicated in Treg trafficking to tumor sites include CXCR4, which drives Treg cells toward tumor site via interactions with CXCL12 that is produced within the tumor microenvironment, as well as CCR8 and CCR10 (86, –88)." (PMID 23874336, 2013). "We performed an in vitro chemotaxis assay with the chemokine ligands for CCR8 and CXCR4 (CCL1 and CXCL12) and observed these chemokines induced more efficient chemotaxis of tumor-infiltrating FoxP3+ T cells compared to their counterparts in lymph nodes." (PMID 22292042, 2012). "It should be noted that, the expression level of CCR8 is not even in the tumor tissues, with relatively higher expression in some tumor tissues, and lower in some other tissues." (PMID 40186298, 2025). "In non-clinical studies using cancer model mice, anti-CCR8 antibodies were shown to deplete tumor-infiltrating Tregs, increase CD8+ T cell infiltration within tumors, and enhance CD8+ T cell functions by upregulating GzmB and IFN-γ expressions 14,17." (PMID 41323783, 2025). "Mechanism of action experiments that designed to find an immunological explanation of RIT and immunotherapy revealed expansion of CD4+CD8+ double positive T cells, anti-tumor M1 macrophages, 4-1BB+ effector CD8+T cells and NK cells after administration of 225Ac-anti-CCR8 RIT." (PMID 41035646, 2025). "CCR8 is preferentially expressed on the cell surface of Tregs that have distributed in tumor tissues but not in peripheral blood." (PMID 40053558, 2025). "Moreover, mature FOXP3+ Tregs in the tumor express CXCR6, IL21R, IL1R1, IL18R1, and, to a lesser extent, CCR8." (PMID 40164596, 2025). "225Ac-anti-CCR8 treatment resulted in modest expansion of M2 macrophages (CT26: p=0.2460, MC38: p=0.0675), however, this cells population was low and represented <5% of total Mφ numbers within the tumor." (PMID 41035646, 2025). "Prior evidence suggests that anti-CCR8 mAbs may selectively deplete intratumoral Tregs, enhance CD8+ T-cell activation, and significantly inhibit tumor growth." (PMID 40508202, 2025). "Another study showed that tumor inhibition was only achieved by means of cell-depleting anti-CCR8 with enhanced ADCC rather than CCR8 blocking antibody." (PMID 40186298, 2025). "In contrast, IPG0521m, which bound murine CCR8 with high affinity and potently blocked CCR8-mediated signaling in different assays, including β-arrestin assay and chemotaxis assay, with a nanomolar range of IC50, was shown to inhibit tumor growth in a dose-dependent manner." (PMID 40186298, 2025). "Mechanistically, this immunosuppressive tumor microenvironment arises from N1-acetylspermidine efflux-dependent SRC signaling activation, which concurrently drives CCL1 macrophage polarization and CCR8 regulatory T-cell recruitment." (PMID 41293149, 2025). "Fc-optimized anti-CCR8 antibodies selectively deplete CCR8-expressing Tregs within tumors without affecting CCR8+ T cells elsewhere, effectively suppressing tumor growth." (PMID 40607438, 2025). "In addition, in tumour tissues, the concentration of TNF-α was positively correlated with the number of TNFR2+CCR8+ Tregs." (PMID 37935468, 2024).